HP (haptoglobin)
Diseases named in the same sentence as HP in open-access papers (continued):
Sharing a sentence is not in itself a finding about the gene and the disease.
ovarian carcinoma (continued). "In addition, several proteins which previously have been shown to be elevated in the serum of ovarian cancer patients such as Chitinase-3-like protein 1(CHI3L1) [Rsc = 4.5], Haptoglobin (HP) [Rsc = 4.0] and Alpha-2-macroglobulin (A2M) [Rsc = 2.5] were elevated in CR." (PMID 27470985, 2016).
type 2 diabetes (27 papers, 2012 to 2026). "The haptoglobin variant in a patient with type 2 diabetes had a significant impact on the concentration of all four activities of SMRIP." (PMID 33114431, 2020). "Our results indicate that people with type 2 diabetes and haptoglobin 2-1 or 2-2 variant have higher levels of selected pro-inflammatory markers and lower anti-inflammatory markers." (PMID 33114431, 2020). "The haptoglobin (Hp) genotype is associated with type 2 diabetes related complications including increased risk for cerebrovascular pathology and worse cognitive performance." (PMID 30809196, 2019). "Haptoglobin has been associated with adiposity and metabolic syndrome, and a predictive role for type 2 diabetes, dependent on BMI, has also been reported." (PMID 30005082, 2018). "This cohort study assesses the association of haptoglobin genotypes with cognitive function and decline in elderly African American adults with type 2 diabetes." (PMID 30646354, 2018). "Is the haptoglobin genotype associated with cognition in African American adults with type 2 diabetes?" (PMID 30646354, 2018). "The haptoglobin gene polymorphism may contribute to cognitive impairment in African American adults who have type 2 diabetes." (PMID 30646354, 2018). "Therefore, the aim of the study was also to assess whether the haptoglobin variant is associated with an increased risk of diabetic complications, including cardiovascular disease, in people with type 2 diabetes." (PMID 33114431, 2020). "However, we believe that haptoglobin phenotyping in people with type 2 diabetes may identify people with an increased risk of diabetic complications, including cardiovascular disease." (PMID 33114431, 2020). "In the case of patients with type 2 diabetes, the particular type of haptoglobin (Hp), an antioxidant protein, is an indicator of cardiovascular problems." (PMID 36552611, 2022). "The HP 1/1 genotype was associated with poorer cognitive function and greater cognitive decline than other HP genotypes in a sample of 466 African Americans with type 2 diabetes." (PMID 33804025, 2021). "Our study provides new evidence for the relationship between the type of haptoglobin in a patient with type 2 diabetes and the concentration of SMRIP." (PMID 33114431, 2020). "For the first time, our research showed the dependence of the haptoglobin phenotype on the concentration of specific pro-inflammatory markers in the blood in patients with type 2 diabetes." (PMID 33114431, 2020). "Based on the obtained results, we calculated the incidence of haptoglobin phenotypes in the population of patients with type 2 diabetes." (PMID 33114431, 2020). "In this cohort study of 466 African American adults with type 2 diabetes, haptoglobin 1-1 carriers had the poorest cognitive function, while haptoglobin 2-1m carriers had the highest cognitive function." (PMID 30646354, 2018). "Another study analyzed haptoglobin in urine and found that this biomarker can predict mortality risk in patients with type 2 diabetes independent of traditional risk factors." (PMID 40430166, 2025). "In addition, water T2 is strongly and inversely correlated with complement C3, C4, fibrinogen, and haptoglobin, markers predictive of incident type 2 diabetes." (PMID 30237882, 2018). "In a prospective study, fibrinogen, complement C3, C4 and haptoglobin were associated with insulin resistance and incident type 2 diabetes, but not α1-antitrypsin, ceruloplasmin or orosomucoid." (PMID 29258604, 2017).
type 2 diabetes (continued). "With regard to the HP alleles, divergent HP1-1 associations with cognitive function have been reported to differ between Ashkenazi Jews and non-Ashkenazi Jews with type 2 diabetes." (PMID 35003209, 2021). "In this part of the work, the relationship between individual clinical parameters, haptoglobin phenotypes and concentrations of SMRIP and the presence or absence of cardiovascular disease in patients with type 2 diabetes was analyzed." (PMID 33114431, 2020).
acute kidney injury (24 papers, 2013 to 2026). Sudden and sustained deterioration of the kidney function characterized by decreased glomerular filtration rate, increased serum creatinine or oliguria. "Previous studies have indicated that perioperative serum haptoglobin levels are associated with the risk of Acute Kidney Injury (AKI)." (PMID 40743649, 2025). "For example, in cardiac surgery patients, intraoperative administration of haptoglobin was independently associated with a lower risk of postoperative acute kidney injury." (PMID 40429487, 2025). "Specifically, haptoglobin administration has been associated with a reduced incidence of acute kidney injury, likely by preventing hemosiderin deposition in renal tubular cells." (PMID 40429487, 2025). "In cardiac surgery, haptoglobin administration was associated with a significant reduction in postoperative acute kidney injury (AKI) (adjusted OR = 0.54)." (PMID 41625885, 2025). "Furthermore, the elevated levels of Hb cause a reduction in free-haptoglobin levels and can overwhelm the mononuclear phagocytic system, the spleen and eventually the kidneys, which may lead to acute kidney injury." (PMID 30558289, 2018). "Logistic regression analysis identified low haptoglobin levels (odds ratio [OR] 27.1), advanced age (OR 1.2), and stage 3 acute kidney injury (OR 22.2) as significant predictors of mortality." (PMID 40429487, 2025). "Haptoglobin was identified as a biomarker for uranium nephrotoxicity, membranous nephropathy, acute kidney injury (Zager, Vijayan & Johnson, 2012), diabetic nephropathy, bladder carcinoma, hepatic fibrosis and acute phase response." (PMID 28560103, 2017). "Moreover, elevated haptoglobin levels in plasma and urine have been also identified in several different murine models of acute-kidney injury." (PMID 39953336, 2025). "Increased plasma concentrations of circulating cell-free hemoglobin (CFH) are supposed to contribute to the multifactorial etiology of acute kidney injury (AKI) in critically ill patients while the CFH-scavenger haptoglobin might play a protective role." (PMID 35193645, 2022). "Initial workup was suggestive of intravascular and microangiopathic hemolysis (elevated lactate dehydrogenase (LDH), reticulocyte count, low haptoglobin, schistocytes present on PBS), renal failure (elevated Cr), and hypercoagulability (low protein C and S)." (PMID 40535396, 2025). "Firstly, the observational design of the study confines the present analysis to the correlation between haptoglobin levels and Acute Kidney Injury (AKI), rather than determining causality." (PMID 40743649, 2025). "In this study, prompt administration of intravenous haptoglobin effectively resolved symptoms in all cases without progression to renal failure." (PMID 39941576, 2025). "For instance, renal failure was found in mice lacking haptoglobin." (PMID 37057066, 2023). "All patients exhibited an acute renal failure (median plasma creatinine level: 3.4 mg/dl [2.4-5.5]) and mechanical, non immune haemolytic anaemia (median Hb: 7.6 g/dl [7.1-8.9], median LDH: 1012 UI/L, and haptoglobin was not measurable)." (PMID 23298275, 2013).
Hyperbilirubinemia (22 papers, 2015 to 2026). An increased amount of bilirubin in the blood. "Chu et al30 stated that significant decrease of haptoglobin concentrationwith lactate dehydrogenises increasing immediately after operations suggests thatpostoperative hyperbilirubinemia is caused by an unconjugatedbilirubin load." (PMID 26191391, 2015). "Labs revealed hemoglobin of 10.2 g/dL (nadir 7.0), platelets of 109 × 109/L, LDH of 1129 U/L (Ref: 122-222 U/L), undetectable haptoglobin, indirect hyperbilirubinemia, and elevated reticulocytes." (PMID 42257063, 2026). "Blood tests showed moderate hemolytic anemia with macrocytosis, reticulocytosis, hyperbilirubinemia, and decreased haptoglobin, consistent with hemolysis." (PMID 38539245, 2024). "Other laboratory investigations, such as persistently dropping Hb, hyperbilirubinemia, low haptoglobin, and high LDH, and reticulocyte count, emphasize the presence of DCT-negative hemolytic anemia." (PMID 39295707, 2024). "Hyperbilirubinemia with predominantly free bilirubin is also noted in G6PD hemolytic anemias with collapsed haptoglobin." (PMID 36845240, 2022). "In our review, hemolysis was present in all 9 patients, accompanied by markers of hemolysis such as elevated LDH, hyperbilirubinemia, and low haptoglobin levels (<8 mg/dL)." (PMID 31015839, 2019). "They include increased reticulocytes, an indicator of marrow compensatory response, elevated lactate dehydrogenase, a marker of intravascular hemolysis, reduced haptoglobin, and unconjugated hyperbilirubinemia." (PMID 26819490, 2015). "Laboratory workup revealed hemoglobin levels of 5.9 g/dL, elevated lactate dehydrogenase (LDH), hyperbilirubinemia, low haptoglobin, and a positive direct Coombs test for IgG, C3, and poly-specific antibodies, confirming warm autoimmune hemolytic anemia (wAIHA)." (PMID 42064491, 2026). "Laboratory evaluation showed hemolysis with markedly elevated lactate dehydrogenase, undetectable haptoglobin, hyperbilirubinemia, and a peripheral smear demonstrating polychromasia with rare schistocytes and spherocytes, while the direct antiglobulin test (DAT) was negative on two occasions." (PMID 41970138, 2026). "Laboratory tests revealed pancytopenia, unconjugated hyperbilirubinemia, elevated LDH (lactate dehydrogenase), low haptoglobin, and fragmented red blood cells (RBCs) on the peripheral smear, but normal FDP (fibrinogen degradation product) and fibrinogen." (PMID 32670728, 2020). "Laboratory findings indicative of CIHA include indicators associated with hemolytic anemia, such as decreased hemoglobin, reduced haptoglobin levels, elevated LDH, and hyperbilirubinemia, and immunological indicators suggestive of immune-mediated hemolysis like a positive DAT for C3 and/or IgG/IgM." (PMID 39840085, 2024). "Her laboratory evaluations during this event did not reveal hyperbilirubinemia or reduced haptoglobin levels." (PMID 33216844, 2020).
liver fibrosis (21 papers, 2012 to 2025). "In a small liver biopsy study (n = 92 patients with viral and autoimmune hepatitis), haptoglobin was negatively correlated with liver fibrosis stage (r = −0.28, p < 0.01)." (PMID 41010909, 2025). "Like apolipoprotein A-I, decreased haptoglobin levels are correlated with higher degrees of liver fibrosis." (PMID 39521382, 2024). "Several serological markers and imaging techniques have been studied by using platelet count, ALT/AST ratio, prothrombin index, hyaluronate, macroglobulin, and haptoglobin to correctly identify HCV-infected patients with liver fibrosis." (PMID 33996335, 2021). "Total haptoglobin along with other proteins is an acceptable marker to diagnose liver fibrosis and also known to decrease in fibrosis." (PMID 33585012, 2020). "Here, we preliminarily validated the relationship between plasma ApoA1, ApoA4, as well as haptoglobin and liver fibrosis to judge which plasma biomarker is better for the early detection of liver fibrosis." (PMID 29179490, 2017). "Total haptoglobin is known to decrease in fibrosis and is presently used along with other proteins to diagnose liver fibrosis." (PMID 22761838, 2012). "Serum haptoglobin is negatively correlated with markers of liver fibrosis." (PMID 41010909, 2025). "Serum ferritin was positively correlated with liver enzymes, LRS, FNI, and ION (markers of liver fibrosis and steatosis), while haptoglobin had a negative association with LRS and FNI in the multivariable analyses." (PMID 41010909, 2025). "Interestingly, alpha 2 macroglobulin and haptoglobin are known to act as markers of fibrosis in the liver, and together with ApoA-I and some key liver enzymes are being used in algorithms that stage liver fibrosis and predict its progression." (PMID 29849043, 2018). "We calculated the AUC value and showed that ApoA4 (area under curve: 0.966) and haptoglobin (area under curve: 0.887) might be the good biomarkers for the early identification of liver fibrosis." (PMID 29179490, 2017). "In this regard, haptoglobin has previously been reported as a serum marker of fibrosis in chronic hepatitis C patients, where it is believed that liver fibrosis leads to increased expression of hepatocyte growth factor promoting a subsequent decrease in haptoglobin levels." (PMID 25580050, 2014). "Furthermore, patients with advanced fibrosis and with indeterminate risk presented lower haptoglobin levels compared to patients without liver fibrosis, as follows: 1.59 ± 0.51 (1.54 [0.54]) g/L vs. 1.65 ± 0.63 g/L vs. 1.91 ± 0.44 g/L, p = 0.0038." (PMID 41010909, 2025). "Hemolytic stress in haptoglobin-hemopexin double-null mice, but not single knock-out mice, causes pronounced fibrosis suggesting that both haptoglobin and hemopexin, which was also identified in this study, are important for protection from liver fibrosis." (PMID 22761838, 2012). "Serum ferritin levels were correlated with LRS (β = 0.190 [0.001; 0.003], p < 0.001), liver fibrosis (Fibrotic NASH Index) (β = 0.198 [0.000; 0.001], p < 0.001), and steatosis, while haptoglobin concentrations were correlated negatively with them." (PMID 41010909, 2025). "Indirect markers of liver fibrosis include specific transaminases or molecules such as α2-macroglobulin, apolipoprotein A1, haptoglobin, γ-glutamyl transpeptidase (GGT) and bilirubin, which are components of a common assay of liver fibrosis known as Fibrotest." (PMID 27458976, 2016). "The univariate prognostic value of apolipoprotein-A1 was confirmed but to our knowledge, it was the first time that its prognostic value persisted after adjustment by age, a marker of acute inflammation (haptoglobin), a sensitive marker of liver injury (GGT), and a marker of liver fibrosis (A2M)." (PMID 33216772, 2020).
liver fibrosis (continued). "We have shown here that haptoglobin levels were lower in patients with advanced liver fibrosis compared to patients without markers of fibrosis, and they correlated independently in a negative manner with FNI and LRS, which is in accordance with previously published data." (PMID 41010909, 2025). "Various other non-invasive methods to assess NAFLD including Steato Test and Fibro Test have been validated to evaluate steatosis and liver fibrosis, but we initially did not measure α2-macroglobulin and haptoglobin which were components of Steato Test and Fibro Test." (PMID 30349997, 2019).
hepatocellular carcinoma (19 papers, 2007 to 2025). A malignant tumor that arises from hepatocytes. "For all these reasons, high levels of HP are associated to poor prognosis in several cancer types, such as ovarian, colorectal, pancreatic, breast and hepatocellular carcinomas." (PMID 35216175, 2022). "By analyzing the haptoglobin protein expression in patients with hepatocellular carcinoma using immunohistochemical staining, it was observed that this protein was highly expressed in adjacent non-tumorous cells, but rarely detectable in the tumor tissue." (PMID 38201509, 2023). "Quantitative analysis of purified haptoglobin N-glycans indicated an increase in bi-fucosylated glycans in hepatocellular carcinoma patients, providing a potential use as a marker for the detection of early stage hepatocellular carcinoma patients." (PMID 27725718, 2016). "Haptoglobin glycosylation has been investigated in previous studies, comparing hepatocellular carcinoma patients originated from ALD, hepatitis C and hepatitis B virus infection." (PMID 27725718, 2016). "Previous studies in humans and in a human hepatoma cell line exposed to hypoxia found that haptoglobin expression was up-regulated; opposite the tendency to lower serum haptoglobin levels found in relation to Darbepoietin-α/rHuEpo treatment in our studies." (PMID 25679398, 2015). "For example, haptoglobin and its glycosylated forms have been identified as potential biomarkers for non-small cell lung cancer and hepatocellular carcinoma, calcitonin for thyroid cancers, and gastrin for gastric and colorectal cancers." (PMID 19860894, 2009). "Fucosylation of serum proteins has been reported as tumor marker on IgG and α-fetoprotein in hepatocellular carcinoma and haptoglobin in pancreatic cancer." (PMID 17488527, 2007). "The selected examples are diminished haptoglobin values in hepatocellular carcinoma, reduced hemopexin levels in prostate cancer patients, and downregulated ceruloplasmin in adrenocortical and hepatocellular carcinomas." (PMID 38201509, 2023). "In some cases, suitability of fucosylated epitopes for cancer management has been utilized, e.g., fucosylated α-fetoprotein has been established as a marker for early detection of hepatocellular carcinoma; fucosylated haptoglobin has been also approved as biomarker for pancreatic and colon cancer." (PMID 34681197, 2021). "Besides, it is revealed that the overexpression of HIF1α is associated with the upregulated HP under the hypoxia condition in human hepatoma cells, suggesting that HP may be secreted by nearby cancer cells under the hypoxia." (PMID 31217907, 2019). "Three identical tissue chips,containing liver and normal adjacent tissues from 31 patients with hepatocellular carcinoma, were analyzed to compare the expression levels of AFP, ORM1 and HP." (PMID 36096917, 2022). "The decreased level of sialylation of haptoglobin and alpha 1-antitrypsin was observed in HCV infected patients as evaluated by ELISA using SNA, whereas the increased level of sialylation was observed in hepatocellular carcinoma." (PMID 32685058, 2020).